RAC1 (Rac family small GTPase 1)
Diseases named in the same sentence as RAC1 in open-access papers (continued):
Sharing a sentence is not in itself a finding about the gene and the disease.
tumor (continued). "Indeed, Rac1 activation at junctions seems to be conducive to trans-endothelial cell migration of both tumour cells and lymphocytes." (PMID 36444960, 2022). "Therefore, we considered that denosumab administration caused activation of Rac1 and triggered the nuclear localization of β-catenin, followed by osteoblastic differentiation of GCTB-SCs, ultimately resulting in the cessation of tumor activity." (PMID 35927428, 2022). "Since we have demonstrated that MG53 exerted the anti-tumor effect by inhibiting RAC1-MAPK pathway, thus we further try to clarify whether MG53 could play a role in the response to sorafenib treatment in HCC." (PMID 35858925, 2022). "Rac1 is a major actor of the crosstalk between the inflammatory state and tumor cell migration." (PMID 35740379, 2022). "Rac1 has been documented to be ubiquitously expressed among a wide range of tumour samples." (PMID 36377725, 2022). "Thus, the overexpression of the dephosphorylated form of TFEB delays tumor growth driven by Rac1, showing a positive activation of the Rac1-TFEB axis in tumorigenesis." (PMID 35159248, 2022). "We have verified that MG53 catalyzed the K48-linked poly-ubiquitination and degradation of RAC1 at Lys5, and we further tried to define whether MG53 exerted its anti-tumor effect via its ubiquitous modification at Lys5 residue of RAC1." (PMID 35858925, 2022). "These differential effects of Rac1 inhibition on normal and tumor cells could be due to the discrepancy in the basal expression level and gene sequence of Rac1 in different kinds of cells." (PMID 35031595, 2022). "1A-116 was able to modulate the Rac1 signaling pathway and affect Rac1-driven cell activities such as cell proliferation, cell cycle progression, cell invasion, and apoptosis in different tumor models." (PMID 36230732, 2022). "Moreover, the effects of LAPTM5 on tumor migration and invasion were eliminated following RAC1 inhibitor treatment." (PMID 36385959, 2022). "In addition, miR-371b-overexpressing xenograft tumors showed decreased expression of CSDE1 and Rac1 compared to the miR-con tumor." (PMID 35490208, 2022). "In fact, inhibition of prenylation is effective against Ras-driven and Rac1-hyperactivated tumours." (PMID 34971971, 2022). "Biological processes coordinated by RAC1 in tumor cells are achieved through the regulation of RAC1 activity and the spatiotemporal activation of RAC1, switching between active and inactive states at different subcellular locations, including the nucleus, plasma membrane, and mitochondria." (PMID 35013128, 2022). "RAC1 also plays important roles in tumor biology by modulating cell processes." (PMID 36452505, 2022). "Our data demonstrate that miR-371b-5p is a tumor-suppressive miRNA that regulates the CSDE1/Rac1 axis and could be a potential prognostic biomarker for TNBC." (PMID 35490208, 2022). "Our study found seven downstream factors that may be associated with chemoresistance, LTF, SOD2, STAT1, CDKN2A, CD81, RAC1, and NDRG1 and five factors that may be associated with tumor development, CCN1, DCTN3, MUC1, H1-5, and SLC1A5." (PMID 35421932, 2022). "We have identified a tumor suppressor role of MG53 and its negative regulation of RAC1 signaling, and then we further try to demonstrate whether the anti-tumor effect of MG53 is mediated through RAC1-MAPK signaling." (PMID 35858925, 2022). "Rac1 is widely expressed, especially in malignant tumor tissues." (PMID 35682879, 2022). "First, a subcutaneous tumor-bearing nude mice model was constructed with Rac1-SH or Rac1-NC LLC." (PMID 35031595, 2022). "This leaves the possibility that the dual function of Par3 could be influenced by Tiam1/Rac1 depending on tumor type." (PMID 35875120, 2022).
tumor (continued). "On the other hand, inhibition of Rac1 could also significantly inhibit the growth of lung tumor, increase the radiation sensitivity of tumor cells." (PMID 35031595, 2022). "It suppresses reversion inducing cysteine rich protein with Kazal motifs (RECK), and inversely upregulates levels of focal adhesion kinase (FAK), Akt, and Rac family small GTPase 1 (RAC1), leading to the formation of tumor protrusions and increasing cell mobility." (PMID 35884446, 2022). "Folate treatment above physiological levels supports epithelial to mesenchymal transition in experimental mouse tumor cells and silencing of RhoA and Rac1, which serve as immediate sensors of folate intracellularly, inhibited the effects of folate on cellular migratory and invasive abilities." (PMID 36198749, 2022). "Taken together, Rac1 inhibition and sorafenib combination prevented tumor growth in vivo." (PMID 35847360, 2022). "RAC1 could affect cellular adhesion, migration, and invasion, and it plays important roles in tumor biology by modulating cell processes." (PMID 36452505, 2022). "Conversely, VEGF-induced Rac1 activation supported trans-endothelial migration of tumour cells." (PMID 36444960, 2022). "Previously, Rac1 has been shown to have high expression in different types of tumors, which was associated with poor prognosis, and its high expression in NSCLC stem cells enhanced the malignant behavior of tumor cells." (PMID 36061144, 2022). "Many studies have shown that Rac1 is an important molecule that mediates tumor cell proliferation." (PMID 35031595, 2022). "RAC1 (Rac family small GTPase 1) is a driver gene that regulates plenty of cellular events, particularly in cell growth and division, cytoskeletal and synaptic recombination, autophagy, and tumor metastasis." (PMID 36404333, 2022). "The reason may be that GLS2 can bind to small GTPase Rac1 and inhibit its interaction with the Rac1 activator guanine nucleotide exchange factor, which in turn inhibits Rac1 and thus favoring the suppression of tumor metastasis." (PMID 35310969, 2022). "The small GTPase RAC1 is known for being a strong mediator of the TGFβ-induced EMT, and EMT-associated functions, such as stem cell generation and cell migration/invasion in PDAC and other tumor types." (PMID 36289908, 2022). "However, low levels of LIMA1 are associated with tumor growth, and LIMA1 binds to the known miR-142 target RAC1 while low levels of Cyclin B1 (CCNB1) are associated with reduced cell growth in accordance with a tumor-suppressive role of miR-142." (PMID 36291816, 2022). "Regarding tumor grade, the higher expression of VEGF-B (log FC = 10.8, p = 0.002), GRB2 (log FC = 2.4, p = 0.01) and RAC1 (log FC = 1.8, p = 0.02) genes were detected in mammary carcinoma tumor tissue, compared to adjacent tissue in group of all breed dogs with tumor grade III (n = 13)." (PMID 34679042, 2021). "Efficient regulation of RAC1 signaling may be required for cell –cell adhesion, tumor cell migration and invasion during metastasis." (PMID 34827551, 2021). "Collectively, the ability of resveratrol to suppress the progression of OSCC may involve activation of the ZNF750/RAC1 signaling pathway and modification of the tumor vascular microenvironment." (PMID 34176441, 2021). "RAC1 expression was substantially higher in tumor tissues than in normal ones (p = 1.9e-12)." (PMID 35493265, 2021). "In this study, the overexpression of TP73-AS1 could facilitate osteosarcoma cell proliferation and invasion in vitro, as well as tumor growth in vivo through competitive binding to miR-142, which could thereby positively regulate RAC1 protein." (PMID 34771549, 2021). "In addition, Rac1, as an entry point to explain the mechanism of drug resistance, also plays a key role in anti-tumor therapy and participates in immune escape mediated by the tumor microenvironment." (PMID 34079763, 2021).
tumor (continued). "Furthermore, in a mutant K-Ras-driven model of papilloma development, tumor tissue exhibited increased levels of Rac–GTP, and loss of one Rac1 copy alone was sufficient to reduce tumor growth and increase survival." (PMID 34071831, 2021). "Also, via the Rac1/RhoA-p38MAPK signaling pathway, IL-8 was found to promote endothelial cell migratory activity, and thereby promoting tumor angiogenesis." (PMID 34294770, 2021). "BCAR1 expression can result in the secretion of more exosomes with high RAC1 expression, which may alter the tumor microenvironment." (PMID 34326687, 2021). "Indeed, intracellular mature IL-37 binds to the CAAX motif in the C-terminal hypervariable region of Rac1, which is normally involved in tumor angiogenesis and metastasis." (PMID 34248996, 2021). "The expression of Rac1 protein in different tumor tissues was detected by immunohistochemistry." (PMID 34079763, 2021). "Collectively, these findings and published results support the conclusion that R-ketorolac preferentially targets Rac1 and Cdc42 which could account for the observed anti-tumor action." (PMID 33413202, 2021). "Rac1 is involved in the regulation of stem cell characteristics of various tumor cells." (PMID 34079763, 2021). "In addition, Rac1 is not only involved in tumor cell cycle, apoptosis, proliferation, invasion, migration, and angiogenesis, but also involved in the regulation of tumor cell stemness, thus promoting the occurrence of tumors." (PMID 34079763, 2021). "To determine whether inhibition of RAC1B might cooperate with EGFR inhibition to increase the efficacy of treatment in human tumour organoids, we designed a Vivo-Morpholino to target human RAC1 exon 4 (hRAC1B PMO)." (PMID 33879799, 2021). "We found that the Cy5.5-conjugated rEgH9 having the highest affinity (KD) of 51 pM dominantly localized around CD31-positive tumor vascular cells, whereas the relatively low-affinity binders, including rA11, rAC1, and rEgA, evenly distributed throughout the tumor." (PMID 33615202, 2021). "Our findings support the notion that TRAF4/6 mediates pro-tumorigenic effects of CD44, and suggests that inhibitors of CD44 signaling via TRAF4/6 and RAC1 may be beneficial in the treatment of tumor patients." (PMID 33804427, 2021). "Therefore, it is of interest to determine if Rac1-induced tumor formation can be avoided with RhoA or YAP/TAZ inhibition." (PMID 34062912, 2021). "It is noteworthy that the rAC1-Cy5.5 conjugates with a moderate affinity (KD) of 3.5 nM exhibited the highest localization and retention in tumor tissue until day 4, even though the radiant efficiency of untreated tumors was almost comparable among all the groups." (PMID 33615202, 2021). "Furthermore, while PLEXIND1 potentially engages SMAD3 and NRP1 to mediate tumor growth in BxPC-3 cells, the involvement of RAC-1 and KRAS is unclear." (PMID 34439202, 2021). "In 2018, a meta-analysis study combining results from 1793 patients indicated that positive RAC1 expression does not relate to histological differentiation but associates with tumor stage, vessel invasion and lymph metastasis." (PMID 33406731, 2021). "Rac1, as an important “commander” of drug resistance in tumor therapy, regulates the drug resistance of tumor cells to targeted drugs by participating in various mechanisms and thus affects the sensitivity of tumor cells to radiotherapy and chemotherapy." (PMID 34079763, 2021). "Cpne3 along with Rac1 is required for cell migration during tumor metastasis." (PMID 34847148, 2021). "Based on the results from this study, we recommend to determine the relative expression of RAC1B and RAC1 in clinical tumor biopsy samples, i.e., by immunohistochemistry, and evaluate their diagnostic value for assessing molecular subtype or predicting invasive potential." (PMID 33567745, 2021). "The critical factor on the basis of this opposing regulation is whether KRT19 could bind to RAC1 in the cytoplasm of tumor cells." (PMID 33767587, 2021).
tumor (continued). "Moreover, RhoA and Rac1/Cdc42 activities, coordinated in regulating both membrane protrusions and cell matrix adhesions, have opposing effects on different modes of tumor cell motility." (PMID 33477952, 2021). "In addition, the expression of PPP1BC, PPP1CC and RAC1 was correlated with the tumor stage (P < 0.05); the expression of PPP1CC and SPP1 was correlated with age (P < 0.05); the expression of PPP1CB was correlated with gender (P < 0.05)." (PMID 33850056, 2021). "Moreover, colorectal tumour RAC1 expression is elevated compared to non-tumour tissue in adjacent gastrointestinal epithelia." (PMID 34830751, 2021). "In addition, RAC1 also inhibits tumor cell apoptosis by increasing intracellular superoxide anions, and plays a critical role in tumor development." (PMID 35493265, 2021). "Our results suggest that the inhibition of CD44 signaling via TRAF4 and RAC1 may be beneficial in tumor treatment." (PMID 33804427, 2021). "Moreover, the promotion of tumor growth by C1GALT1 overexpression was mitigated by silencing of RAC1." (PMID 34307388, 2021). "Inhibition of RAC1 activity could represent an opportunity to develop novel therapeutic approach to target different stages of tumor cell metastasis." (PMID 34827551, 2021). "Intracellular mature IL-37 suppresses tumor metastasis via inhibiting Rac1 activation." (PMID 32226541, 2020). "Therefore, RCC2 inhibits tumor cell metastasis by inhibiting activation of small GTPases, Rac1, and Arf6, and by promoting α5β1-FN-signaling network and cellular recognition to FN concentrations." (PMID 33521058, 2020). "Moreover, when E-cadherin expression switches to P-cadherin, further cytosolic translocation of p120 occurs leading to induction of tumor cell migration through activation of RAC1 and CDC42, tumor anchorage-independence and increased tumor growth in vivo." (PMID 33076339, 2020). "In a previous study, we screened different anthraquinone compounds and a series of tumor proteins with different docking software and scoring functions or algorithms by molecular docking computer-aided drug design and found that Rhein can stably bind Rac1." (PMID 32547389, 2020). "Thus, there appears to be a potential opportunity for the research and development of RAC1-guided inhibitory therapies to manage the tumor progression and resistance in solid tumors." (PMID 32545340, 2020). "Numerous evidences have suggested that RAC1 could emerge as a critical role in tumor for its angiogenic and invasive behaviors." (PMID 31895772, 2020). "Tumor cells under stress (radiation, chemotherapy, etc.)undergo the upregulation of RAC1, which activates a cascade of stress-responsive signals within the cytosol, cell membrane, mitochondria, and/or nucleus to promote the cell survival, proliferation, and migration." (PMID 32545340, 2020). "It is therefore conceivable that depolarization‐dependent Rac1 activation may contribute to metastatic dissemination in response to local ionic changes in the tumor microenvironment." (PMID 31612502, 2020). "Moreover, we described in detail how VEGF also activates RhoA, Rac1, and Cdc42 contributing thus to tumor motility and invasion." (PMID 32377503, 2020). "Dysregulation of RAC1 also results in tumor metastasis through epithelial-mesenchymal-transition." (PMID 33133148, 2020). "Alternatively, it might constitute an adaptive solution to promote the chronic, RAC1-dependent activation of JNK that could contribute to overcome the terminal differentiation-based tumor suppressor mechanism that specifically operates in these cells." (PMID 32963234, 2020). "Finally, the function of ORAI1 as an effector of RAC1 that has been shown here is particularly important since RAC1 drives tumor initiation." (PMID 32313105, 2020). "Therefore, overexpression of RCC2 in tumor cells prevents cellular apoptosis and promotes chemotherapeutic resistance by blocking Rac1 signaling." (PMID 33521058, 2020).
tumor (continued). "The precise roles of calmodulin in Ras-driven tumourigenesis are not fully understood, but Ca2+/calmodulin-induced Rac1 activation may strengthen tumour growth as well as metastasis." (PMID 32456244, 2020). "Rac1 activation and inactivation control plasticity of tumor cell movement." (PMID 32178475, 2020). "The eIF2α-mediated Rac1 pathway also participates in proliferation and survival of tumor cells." (PMID 32708122, 2020). "Furthermore, by screening potential downstream effectors, we found that Porf-2 is able to suppress tumor cell migration by the inactivation of Rac1 and by reducing the expression of MMP-2/9." (PMID 32676454, 2020). "In addition, previous studies by our group showed that hypoxia activates the early endocytic protein, Rab5, thereby allowing Rac1 activation, lamellipodia formation, tumor cell migration, invasion and metastasis." (PMID 33339852, 2020). "Taken together, the data indicated that RAC1 plays a tumor‐promoting role in ESCC cells." (PMID 31314174, 2019). "This causes the activation of VEGFR2 and the trafficking of the α4β1-VEGFR2 complex to the leading edge of the cell where it facilitates tumor, or endothelial cell, migration via Rac1 (Ras-related C3 botulinum toxin substrate 1) activation and the reorganization of the actin cytoskeleton." (PMID 31850210, 2019). "But the RAC1-transformed tumour cells stop cycling upon Arp2/3 inhibition." (PMID 30971746, 2019). "Interestingly, ANGPTL4 is strongly related to angiogenesis and tumor migration via α5β1-integrin/RAC1 interaction." (PMID 31277479, 2019). "Moreover, we found that blocking the SUMO pathway inhibits tumour cell invasion by decreasing RAC1 SUMOylation." (PMID 31578236, 2019). "Cellular processes orchestrated by RAC1 in tumor cells are achieved via the spatiotemporal activation of RAC1 and the regulation of RAC1 activity, switching between active and inactive states at various subcellular locations, including the plasma membrane, nucleus, and mitochondria." (PMID 31027363, 2019). "Similarly, Rac1 in ECs is also responsive to tumor-secreted vasoactive stimuli, resulting in increased vessel permeability and trans-endothelial migration of tumor cells." (PMID 31174284, 2019). "Enhanced Tiam1/Rac1 signaling may increase the transcription of Wnt target genes to promote tumor initiation and progression." (PMID 30171257, 2019). "Moreover, TIPE2 suppressed tumor invasiveness by inhibiting Rac1, leading to decreased expression of uPA and MMP9." (PMID 30186591, 2018). "RAC1 is also involved in tumor invasion, metastasis, and angiogenesis." (PMID 29651441, 2018). "For instance, it was shown that RhoA and Rac1 can cooperate with Ras and Raf in tumor progression." (PMID 30544828, 2018). "Notably, the regulatory protein mutants show a high level of concurrent expression in tumor cells, suggesting that hitting multiple nodes releases key Rac1-regulated pathways from normal control." (PMID 30261690, 2018). "Tiam1/Rac1 signaling is critically involved in tumor cell progression, invasion, and metastasis." (PMID 29416753, 2018). "Moreover, EGFRvIII induces the phosphorylation of Dock180 via protein kinase A, which activates Rac1 and promotes glioma tumor growth and invasion." (PMID 30544910, 2018). "Together, these data indicate that overexpression and aberrant Rac1 and/or Rac1b activity are closely tied to malignant ovarian cancer and further dissection of their respective roles in tumor microenvironment responsiveness, metastasis and relapse is warranted." (PMID 30261690, 2018). "One explanation for this result is that tumor cell polarity reversal might require Rac1 to be activated by β1 integrin." (PMID 29435106, 2018). "Moreover, it has also been demonstrated that Rac1 is involved in regulating apoptosis of tumor cells." (PMID 30534358, 2018). "RAC1 activation is thus needed for in vivo tumor growth of human EGFR-mutant NSCLC cell lines." (PMID 30590030, 2018).